TNF (tumor necrosis factor)
Diseases named in the same sentence as TNF in open-access papers (continued):
Sharing a sentence is not in itself a finding about the gene and the disease.
rheumatoid arthritis (continued). "CDK4/6 inhibitor palbociclib inhibited the proliferative phase of rheumatoid arthritis in an animal model, especially when combined with TNF-a or IL-6 blockers." (PMID 34198899, 2021). "For example, in a mouse model, NFAT activates transcription of the TNFα locus to promote autoimmune diseases such as rheumatoid arthritis, RA." (PMID 33962392, 2021). "In a small group of patients, ACE2 level was significantly lower in the plasma from rheumatoid arthritis (RA) patients on anti-TNF-α treatment compared to healthy control." (PMID 34025650, 2021). "TNFΔARE transgenic mice overexpress TNF and develop inflammation in tissues and organs, and spontaneously exhibit rheumatoid arthritis (RA) and inflammatory bowel disease (IBD)." (PMID 35056521, 2021). "The most commonly enriched KEGG pathways were the chemokine signaling pathway, cytokine-cytokine receptor interaction, toll-like receptor signaling pathway, NOD-like receptor signaling pathway, rheumatoid arthritis, pertussis, and the TNF signaling pathway." (PMID 34233297, 2021). "Based on the importance of TNF-α in rheumatoid arthritis and gout, subtraction analysis of phosphoproteins generated by stimulation with TNF-α after cross-linking CLEC12A from those generated by TNF-α alone was performed." (PMID 34234773, 2021). "In recent years, there has been great progress in the development of new antirheumatic drugs for rheumatoid arthritis, such as TNFα inhibitors, IL-6 receptor antagonists, and inhibitors targeting the JAK pathway." (PMID 34646130, 2021). "TNF-α is a well-known proinflammatory molecule transducing a wide range of signal cascades as a master cytokine in various diseases, including rheumatoid arthritis." (PMID 33915757, 2021). "In summary, this study proved that NG-R1 promoted lymphatic drainage function to ameliorating rheumatoid arthritis in TNF-Tg mice by suppressing NF-κB signaling pathway." (PMID 35280253, 2021). "Due to the key role of TNF-α in systemic inflammation, it has been a target for immunological therapies in autoimmune conditions like inflammatory bowel disease, rheumatoid arthritis, and psoriasis." (PMID 34988343, 2021). "TNF-α regulates osteoclast formation in erosive bone diseases such as rheumatoid arthritis and periodontal diseases where there is an immoderate presence of osteoclasts leading to excessive bone resorption." (PMID 34484587, 2021). "Infliximab, golimumab, etanercept, certolizumab pegol, and adalimumab are five anti-TNF agents that have been documented for the treatment of rheumatoid arthritis." (PMID 34868573, 2021). "Another recent systematic review that took into consideration the duration of anti-TNF therapy evaluated the effect on the periodontal status of rheumatoid arthritis subjects." (PMID 33546101, 2021). "Circulating chemerin levels are increased in various inflammatory diseases such as rheumatoid arthritis and correlate to disease activity and to several circulating pro-inflammatory markers, such as TNF-α, IL-6, and CRP." (PMID 34639186, 2021). "Further, anti-inflammatory effects of crocin by decreasing TNF-α, have been shown in hemorrhagic shock and rheumatoid arthritis." (PMID 33628722, 2021). "The maximum tolerated dose of seliciclib has been defined for rheumatoid arthritis refractory to TNF blockade." (PMID 33928262, 2021). "TNF (Tumor Necrosis Factor) inhibitors have been an important step forward in the treatment of several chronic inflammatory diseases, especially rheumatoid arthritis, and Crohn’s disease." (PMID 34577072, 2021). "Other researchers have also shown that SFN inhibits expression of MMPs in mice with induced arthritis, and reduction of IL-17 and TNF-α levels in T cells from patients with rheumatoid arthritis." (PMID 33515210, 2021). "In this study, for the first time we investigated the Cytos-11 antisense oligonucleotide suppression of TNF-α gene expression in a rat model of rheumatoid arthritis induced by complete Freund’s adjuvant." (PMID 33498456, 2021).
rheumatoid arthritis (continued). "Such small molecule inhibitors of TNF would have a significant impact on the breadth of the patient population able to access treatment for autoimmune diseases such as rheumatoid arthritis and Crohn’s disease." (PMID 33495441, 2021). "Tumor necrosis factor (TNF) and interleukin-1 (IL-1) have been shown to play an essential role in the pathogenesis of inflammatory conditions such as rheumatoid arthritis (RA), psoriatic arthritis (PsA), and ankylosing spondylitis (AS)." (PMID 34790122, 2021). "Scolopendrasin IX, another peptide isolated from the same centipede species, can down-regulate the expression of pro-inflammatory mediators such as TNF-α and IL-6, also having therapeutic effects against rheumatoid arthritis." (PMID 34795699, 2021). "Reducing TNF-α activity has proven efficacy in the treatment of rheumatoid arthritis, and as antisense technologies are now an actively developing industry, the development of an ASO aimed at inhibiting TNF-α is both promising and timely." (PMID 33498456, 2021). "HuR is also involved in the pathogenesis of inflammatory diseases (e.g., rheumatoid arthritis) by binding to the mRNAs of inflammatory cytokines (e.g., TNF-α)." (PMID 35069550, 2021). "It has been shown that E2F2 upregulates IL-1 and TNF-a in rheumatoid arthritis (RA) synovial fibroblasts." (PMID 34198899, 2021). "It was reported that the natural auto-antibodies against CS (anti-CS IgM and IgG antibodies) were increased in rheumatoid arthritis (RA) patients treated with TNF inhibitors, certolizumab or etanercept therapy." (PMID 34517822, 2021). "Cytokine blockade targeting TNF-α and IL-6, have been successfully developed to treat rheumatoid arthritis, while barely any anti-cytokine therapies have been successfully introduced into clinical practice as drugs for SLE patients." (PMID 34768756, 2021). "Targeting TNFα is beneficial in many autoimmune and inflammatory diseases, including rheumatoid arthritis." (PMID 34301319, 2021). "TQ treatment was previously shown to inhibit TNF-α and IL-6 production to limit inflammation in rheumatoid arthritis synovial fibroblasts." (PMID 33920708, 2021). "TNF-α-induced osteoclast formation is a major contributor to bone destruction in disorders such as rheumatoid arthritis and periodontal disease." (PMID 34484587, 2021). "TNF-α, IL-1β, and IL-6 have been well documented for their role in several inflammatory conditions, including lung inflammation, rheumatoid arthritis, and intestinal bowel diseases (IBD)." (PMID 34940701, 2021). "Cytokine inhibitors such as anti-TNF-α, anti-IL-17A, and anti-IL-6 have been used in other inflammatory-driven diseases such as rheumatoid arthritis (RA)." (PMID 34208697, 2021). "Key among the targets is TNF-α as a master regulator of the inflammatory process, and whose targeting in the treatment of rheumatoid arthritis and a broad number of autoimmune disorders has provided a huge improvement in the management of these illness." (PMID 33854417, 2021). "In adjuvant‐induced arthritis, thymoquinone treatment provides protection against rheumatoid arthritis via reducing the expressions of IL‐1b and TNF‐a in adjuvant‐induced arthritis." (PMID 33747489, 2021). "In this study, we screened and isolated the B cells secreting anti-TNFα antibody from patients with rheumatoid arthritis." (PMID 34886761, 2021). "For example, anti-tumor necrosis factor therapy was a breakthrough treatment for autoimmune diseases and is indicated to treat rheumatoid arthritis, Crohn’s disease, ulcerative colitis, psoriasis, or ankylosing spondylitis." (PMID 34235145, 2021). "Part 1 of this phase 1b/2a trial aimed to establish the maximum tolerated dose of seliciclib in patients with active rheumatoid arthritis despite ongoing treatment with TNF inhibitors, and to evaluate safety and pharmacokinetics." (PMID 33928262, 2021).
rheumatoid arthritis (continued). "Several TNF-alpha blockers are approved for use in patients with chronic inflammatory conditions, such as rheumatoid arthritis and inflammatory bowel disease." (PMID 34988343, 2021). "As a treatment, patients suffering from rheumatoid arthritis received a blocking TNF-α agent, etanercept, and adalimumab." (PMID 34209109, 2021). "Most of the data available on the safety of vaccines with concomitant anti-TNF-α administration are related to patients suffering from rheumatoid arthritis or other rheumatological diseases." (PMID 33916122, 2021). "With the use of ADA against tumor necrosis factor-α (TNF-α) inhibitors for treatment of rheumatoid arthritis, TNF-α was detected in a maximum of 87% of cases." (PMID 34871313, 2021). "The first approved human antibody was Humira (adalimumab) targeting tumor necrosis factor (TNF) for the treatment of rheumatoid arthritis." (PMID 33802091, 2021). "The new formulation developed for SSZ as PLGA MPs prepared with α-tocopherol produced a decrease in IL-1, IL-6 and TNF-α levels thereby resulting in an adequate delivery system for the treatment of chronic inflammatory diseases such as rheumatoid arthritis." (PMID 34202859, 2021). "Tumor necrosis factor-alfa (TNF-a) antagonists are extensively utilized in the treatment of inflammatory rheumatic diseases such as rheumatoid arthritis (RA) and ankylosing spondylitis (AS)." (PMID 33535732, 2021). "A nanocomplex, thiolated glycol chitosan (TGC) polymer loaded with poly-siRNA, was targeted to TNF-α, which proved to be very efficient in curing rheumatoid arthritis." (PMID 34451803, 2021). "KEGG pathway analysis showed that candidate DEGs were enriched in rheumatoid arthritis, primary immunodeficiency, Th17 cell differentiation, and TNF signaling pathway." (PMID 34918712, 2021). "TNF-α is an inflammatory cytokine which releases in both acute and chronic inflammation; TNF-α induces pain and fever and plays a role in rheumatoid arthritis, osteoarthritis, and systemic lupus erythematosus." (PMID 33763143, 2021). "Some studies have suggested improvement in the BMD after starting infliximab, a TNF-α antagonist in patients with rheumatoid arthritis." (PMID 34842748, 2021). "This multi-center, retrospective study aimed to clarify retention rates and reasons for discontinuation of either tumor necrosis factor inhibitors (TNFi) or interleukin-6 inhibitors (IL-6i) in patients with elderly-onset rheumatoid arthritis (EORA)." (PMID 33858490, 2021). "We report an unusual case of chronic Q fever involving a hip arthroplasty in an immunocompromised woman treated with tumor necrosis factor (TNF)-α blockers for rheumatoid arthritis." (PMID 35610714, 2021). "KEGG pathway enrichment analysis indicated that genes in cluster-1 enriched in TNF signaling pathway and rheumatoid arthritis." (PMID 34054546, 2021). "Our aim was to determine the maximum tolerated dose of seliciclib in patients with active rheumatoid arthritis despite treatment with TNF inhibitors, either as monotherapy or with background conventional synthetic DMARDs." (PMID 33928262, 2021). "The ability of CLEC12A to regulate signal transduction pathways activated by TNF-α suggests our findings are applicable to other inflammatory diseases, such as rheumatoid arthritis." (PMID 34234773, 2021). "Tumor necrosis factor-α (TNF-α) is a drug target in rheumatoid arthritis and several other auto-immune disorders." (PMID 33671607, 2021). "Taken together, TNF humanized mouse models that partially mimic inflammatory conditions in patients with autoimmune disorders, such as rheumatoid arthritis and psoriasis, were generated and evaluated." (PMID 34054827, 2021). "An lncRNA–mRNA-weighted co-expression network analysis demonstrated the mechanism of Caulophyllum robustum Maxim against rheumatoid arthritis through lncRNA-mediated signal pathways including TNF, Toll-like receptor, and chemokine signaling pathways." (PMID 33929970, 2021).
rheumatoid arthritis (continued). "Administering recombinant IL-1 receptor antagonist or monoclonal antibodies against TNF-α or IL-6 or their receptors has proved beneficial in clinical therapy of patients with rheumatoid arthritis." (PMID 34445536, 2021). "Circulating resistin has been positively correlated with C-reactive protein (CRP), TNF-α, and IL-6 in type 2 diabetes, rheumatoid arthritis, chronic kidney disease, sepsis, and coronary atherosclerosis." (PMID 34639186, 2021). "During macrophage process, TNF‐α promotes the rheumatoid arthritis while supplementation of thymoquinone (1‐5 μM) significantly suppressed the IL‐8 production, TNF‐α‐induced IL‐6 and VCAM‐1, ICAM‐1, and cadherin‐11 (Cad‐11) expression." (PMID 33747489, 2021). "Our findings demonstrated that SJT strongly alleviated rheumatoid arthritis and reduced the secretion of IL-6, IL-1β, TNF-α of AIA rats." (PMID 34393779, 2021). "TNF is a key regulator of inflammation in rheumatoid arthritis and other inflammatory diseases, and TNF antagonists are commonly used to treat inflammatory conditions." (PMID 33373873, 2021). "TNF-alpha, IL-1beta, CXCL8, and CXCL10 levels have been linked with ankylosing spondylitis and crystal, psoriatic and rheumatoid arthritis." (PMID 35153741, 2021). "For example, Etanercept, a ligand trap that targets TNFα, is used successfully in rheumatoid arthritis patients." (PMID 34153320, 2021). "Anti-TNF-α therapy in patients with rheumatoid arthritis leads to the reduction of other pro-inflammatory mediators, such as IL-1β and IL-6, causing an improvement in the anti-inflammatory effect." (PMID 34959607, 2021). "In other diseases (such as rheumatoid arthritis or diabetes mellitus), chemerin levels positively correlated with many pro-inflammatory factors, including TNF." (PMID 34640632, 2021). "Elevated IL-17B levels have been reported in the synovial tissues of rheumatoid arthritis patients, which can promote TNF-α-induced G-CSF and IL-6 expression in fibroblasts." (PMID 33545363, 2021). "In order to develop TNFα antibodies with low immunogenicity and with functions similar to that of human antibodies, we screened and isolated anti-TNFα-positive B cells from patients with rheumatoid arthritis." (PMID 34886761, 2021). "Despite the success of TNF-inhibitor therapy in rheumatoid arthritis treatment, up to 40% of patients fail to respond adequately." (PMID 33691749, 2021). "While there exist differences in affinity and binding valency to TNFα among TNFis, their efficacy and safety profile in rheumatoid arthritis are very comparable." (PMID 34301319, 2021). "A different thapsigargin schedule, 0.4 mg/kg/injections 3 times per week, is tolerated and effective in reducing Notch1 signaling in TNF-induced synovial M1 macrophages in a Hes1-GFP/TNF transgenic mouse model of rheumatoid arthritis." (PMID 33407740, 2021). "TNF inhibitors are a class of biopharmaceuticals applicable for treating Crohn's disease, ulcerative colitis, rheumatoid arthritis, ankylosing spondylitis, psoriatic arthritis, plaque psoriasis, and/or juvenile idiopathic arthritis." (PMID 34877355, 2021). "Meanwhile, elevated TNF-α and IL-6 stimulate the expression of rheumatoid arthritis-related proteins such as C-reactive protein." (PMID 34108880, 2021). "For example, inhibition of endogenous TNF-α is a standard of care for chronic inflammatory diseases such as ulcerative colitis, Crohn’s disease, rheumatoid arthritis, and several other diseases." (PMID 33986746, 2021). "The increase in levels of inflammatory cytokines such as tumor necrosis factor-alpha (TNF-α), IL-1β, and IL-6, play an essential role in rheumatoid arthritis." (PMID 34899343, 2021). "In this study, ASO Cytos-11 selectively reduced levels of TNF-α in the peripheral blood and cell membranes and reduced joint swelling in rats with rheumatoid arthritis with an efficacy similar to that of adalimumab." (PMID 33498456, 2021).
rheumatoid arthritis (continued). "TNF-α is also closely related to the mechanisms of speeded up atherosclerosis in rheumatoid arthritis." (PMID 34209109, 2021). "TNF-alpha is a cytokine known to cause inflammation and related symptoms in several chronic inflammatory diseases, such as rheumatoid arthritis (RA), ankylosing spondylitis (SpA), psoriatic arthritis (PsA), plaque psoriasis, Crohn’s disease (CD), and ulcerative colitis (UC)." (PMID 33953678, 2021). "For example, EVs isolated from synovial fibroblasts of rheumatoid arthritis patients exhibit tumor necrosis factor (TNF)-α in their surface, which delays T cell-mediated apoptosis." (PMID 34830171, 2021). "Anti-Tumor Necrosis Factor Trial in Rheumatoid Arthritis with Concomitant Therapy Study Group Anti-Tumor Necrosis Factor Trial in Rheumatoid Arthritis with Concomitant Therapy Study G, Infliximab and methotrexate in the treatment of rheumatoid arthritis." (PMID 33909773, 2021). "Adalimumab is a TNF-α inhibitor that is used for the treatment of autoimmune diseases such as rheumatoid arthritis." (PMID 34030135, 2021). "Currently, five anti-TNF therapeutics and additional biosimilars thereof are approved and successfully used to treat autoimmune diseases, including rheumatoid arthritis (RA), juvenile RA, inflammatory bowel disease, psoriasis, and ankylosing spondylitis." (PMID 34305946, 2021). "Similar improvements in microarchitectural parameters and bone strength were observed in a transgenic tumor necrosis factor (TNF)-α model of rheumatoid arthritis with the same doses of tart cherry supplementation." (PMID 33562341, 2021). "For example, IL-17A and IL-22 are believed to act in concert in autoimmune pathogenesis and IL-17 has been shown to act synergistically with TNF-α, in the induction of IL-6 in rheumatoid arthritis." (PMID 34203644, 2021). "For GSE46750, 41 considerably enriched pathways (FDR < 0.05) were identified, including the IL-17 signaling pathway, TNF signaling pathway, rheumatoid arthritis, serotonergic synapse, and cellular senescence." (PMID 33912052, 2021). "Not surprising in view of its ability to interact with TNFR2, LTα2β is inhibited by Etanercept, which is approved for the treatment of rheumatoid arthritis and also inhibits TNF and LTα." (PMID 33824270, 2021). "A variety of cytokines act critical roles, such as tumor necrosis factor (TNF-α), in osteoarthritis (OA) or rheumatoid arthritis (RA)." (PMID 34943075, 2021). "At present, most of the researches on tumorigenicity of biologics are on TNF-α inhibitors for the treatment of rheumatoid arthritis, but few are in SpA." (PMID 34776944, 2021). "Observational studies have also revealed a decreased incidence of MI and stroke in patients receiving anti-TNF therapies for rheumatoid arthritis compared to immunologic naive patients." (PMID 34988343, 2021). "The biological processes of the upregulated 115 genes were enriched mainly in the TNF signaling pathway (2.83 × 10–5), NF-κB signaling pathway (6.02 × 10–3), influenza A (1.52 × 10–2) and rheumatoid arthritis (3.77 × 10–2)." (PMID 33520118, 2021). "A role for TNF-α in suppressing systemic autoimmune responses has been emphasized by anti-TNF-α therapies for rheumatoid arthritis and inflammatory bowel disease patients." (PMID 34712661, 2021). "This framework applied to rheumatoid arthritis (RA) revealed that activation of the TNF pathway in CD4+ T cells plays a vital role in RA etiology." (PMID 33557957, 2021). "HAART: highly active antiretroviral treatment, RA: rheumatoid arthritis, TNF-α: tumor necrosis factor-alpha, CD4+ T: cluster of differentiation-4 +T, RNA: ribonucleoprotein." (PMID 33209528, 2020). "In patients with rheumatoid arthritis, miR-9-5p is downregulated by IL-6 and TNF-α and has a preventive effect on the development of peripheral neuropathy." (PMID 32751105, 2020).